HSPA5 (heat shock protein family A (Hsp70) member 5)
Diseases named in the same sentence as HSPA5 in open-access papers (continued):
Sharing a sentence is not in itself a finding about the gene and the disease.
glioma (continued). "Since HSPA5 is a master chaperone that could be upregulated by ATF4 during ER stress, we examined the impact of ATF4 knockdown on HSPA5 expression in DHA-treated glioma cells." (PMID 31519193, 2019). "Silencing HSPA5 by siRNAs suppressed GPX4 expression in glioma cells." (PMID 31519193, 2019). "Dihydroartemisinin could attenuate ferroptosis via the PERK/ATF4/HSPA5 pathway in glioma cells." (PMID 35372041, 2022). "Additionally, in both in vivo and in vitro models of glioma, the mechanism by which dihydroartemisinin exerts anticancer effects on glioma cells was found to be dependent on promoting ferroptosis via the PERK–ATF4–heat shock protein family A member 5 (HSPA5)–GPX4 pathway." (PMID 35082783, 2021). "Moreover, inhibition of HSPA5 or PERK showed a synergistic anticancer effect with DHA in glioma." (PMID 31519193, 2019). "Bioinformatics analysis using TIMER2.0 and GEPIA 2.0 revealed positive correlations between CLU expression and several genes (BAX, BCL2L1, PRNP, HSPA5, LRP2, TTR, all p < 0.05), suggesting synergistic or antagonistic interactions during glioma development." (PMID 40606578, 2025). "Additional studies have demonstrated that the ATF4-induced expression of HSPA5, also known as BiP, can prevent GPX4 degradation and protect against ferroptosis in pancreatic ductal adenocarcinoma and glioma cells." (PMID 40227255, 2025). "P2X7 activation stimulated C6 glioma cell proliferation and survival in vitro and increased expression of pro-survival proteins, such as HSPA1, HSPA5 chaperones, and CD133 as well as p38 MAPK and AKT kinase phosphorylation." (PMID 34964926, 2022). "The upregulation of HSPA5 increases the expression and activity of GPX4, GPX4 protects glioma cells from ferroptosis by neutralizing DHA induced lipid peroxidation." (PMID 35478955, 2022). "We also collected some clinical specimens to verify the expression of HSPA5 and MTPN in glioma and normal brain tissue." (PMID 34026352, 2021). "Upregulated ATF4 increases the expression of HSPA5 and activity of glutathione peroxidase 4 (GPX4), thus protecting glioma cells from ferroptosis." (PMID 34163322, 2021). "HSPA5 and MTPN are possible biomarkers of gliomas suitable for all populations to improve the prognosis of these patients." (PMID 34026352, 2021). "qRT-PCR and Immunohistochemistry assay indicated that HSPA5 and MTPN over-expressed in Glioma samples compared to normal samples." (PMID 34026352, 2021). "Heat shock protein family A member 5 (HSPA5) can upregulate the expression and activity of GPX4 to prevent dihydroartemisinin-induced ferroptosis in glioma." (PMID 33868986, 2021). "Our study suggests that HSPA5 and MTPN are possible biomarkers of gliomas suitable for all populations to improve the prognosis of these patients." (PMID 34026352, 2021). "However, whether HSPA5 regulates ferroptosis in glioma cells remains unclear." (PMID 31519193, 2019). "Furthermore, our data uncovered that the HSPA5 and NRF2 signalling pathways mediate the effects of borax on glioma cells, playing a crucial role in regulating cellular responses to oxidative stress and serving as key players in ferroptosis regulation." (PMID 38494858, 2024). "In addition, HSPA5 knockdown partially alleviated the proliferation, migration, and invasion in SF126 glioma cells induced by LIMD1-AS1 overexpression." (PMID 37385987, 2023). "HSPA5 has the effect of up-regulating the GPX4, which results in protecting glioma cells from ferroptosis, indicating the activation of ATF4 strengthens the drug resistance of glioma." (PMID 35784729, 2022). "By real-time quantitative PCR detection, compared with normal brain tissue (0.96 ± 0.28), the expression of mRNA HSPA5 in WHO II gliomas and WHO III/IV glioma tissue both increased significantly (1.25 ± 0.32,1.85 ± 0.70), and the differences were statistically significant (P < 0.05)." (PMID 34026352, 2021).
glioma (continued). "We began with the master regulator of the UPR, GRP78 (HSPA5), the expression of which correlates with poorer survival of GBM patients and was previously reported to confer chemoresistance in glioma cells." (PMID 32433555, 2020). "In contrast, overexpression of HSPA5 inhibited DHA-induced ROS, MDA and lipid ROS generation and cell death in glioma cells, suggesting that ATF4-induced HSPA5 might antagonize the pro-ferroptotic activity of DHA." (PMID 31519193, 2019). "Previous studies have demonstrated that HSPA5 expression is elevated in glioma specimens and silencing HSPA5 increases temozolomide chemosensitivity in malignant glioma cell lines, suggesting the potential roles of UPR in glioma chemoresistance." (PMID 31519193, 2019). "Moreover, HSPA5 silencing enhanced DHA-induced ferroptosis, while HSPA5 overexpression had an opposite effect in glioma cells, which is similar to the fidings in pancreatic cancer cells." (PMID 31519193, 2019). "Subsequent HSPA5 upregulation increased the expression and activity of glutathione peroxidase 4 (GPX4), which neutralized DHA-induced lipid peroxidation and thus protected glioma cells from ferroptosis." (PMID 31519193, 2019). "Since HSPA5 protected glioma cells from DHA-induced ferroptosis, we hypothesized that HSPA5 inhibition could enhanced the anticancer capacity of DHA." (PMID 31519193, 2019). "Moreover, suppression of HSPA5 expression by siRNA significantly increased ROS, MDA and lipid ROS levels as well as cell death in glioma cells treated with DHA." (PMID 31519193, 2019). "Notably, GPX4 restoration significantly counteracted with the enhancement of DHA-induced ROS, MDA and lipid ROS production as well as cell death rate by HSPA5 silencing in both U251 and U373 cells, suggesting that GPX4 mediated the anti-ferroptotic effects of HSPA5 against DHA in glioma cells." (PMID 31519193, 2019). "In the absence of DHA, the basal levels of ROS and MDA in glioma cells are very low and could not be potentiated by knockdown of PERK, ATF4 and HSPA5." (PMID 31519193, 2019).
melanoma (81 papers, 2008 to 2025). A malignant, usually aggressive tumor composed of atypical, neoplastic melanocytes. "The presence of HSPA5 at the cell surface is therefore a hallmark of some cancer cells, including melanoma cells, and cell surface HSPA5 regulates various oncogenic processes, including stemness, proliferation, migration, angiogenesis, and invasiveness." (PMID 37807968, 2023). "The HSPA5 inhibitor HA15 has previously been shown to inhibit melanoma development in mice by enhancing cancer cell death, in particular in cells with high HSPA5 levels." (PMID 37807968, 2023). "In parallel, the overexpression of SIRT7 in WM35 melanoma cell line resulted in up-regulation of IRE1α expression, IRE1α phosphorylation, spliced XBP1 expression, and HSPA5 expression caused by TM treatment, but marginal influence on ATF6 and phosphorylated-PERK." (PMID 36918544, 2023). "Correspondingly, HSPA5 has been reported to be up-regulated in tumors of various organs such as breast, liver, stomach, esophagus, brain, prostate, head and neck, and melanoma, and may be accompanied by aggressive tumor behavior and recurrence." (PMID 34580365, 2021). "MS-based profiling of exosomes, ectosomes, and apoptotic bodies derived from mouse B16-F1 melanoma in GO analysis revealed the enrichment of histones (H2A, H2B, H3.1, and H4) and heat shock proteins (HSPA5 and HSC71) in exosomes compared to ectosomes and apoptotic bodies." (PMID 31086060, 2019). "Resistance of melanoma cells to the BRAFV600E inhibitor, PLX4032, is reversed by inhibiting the protein chaperone HSPA5." (PMID 40667288, 2025). "This is consistent with findings obtained with melanoma cells, where HA15 was more effective when the concentration of HSPA5 was high." (PMID 37807968, 2023).
colon carcinoma (80 papers, 2012 to 2026). "Further studies are required to corroborate the involvement of ER stress and the UPR in the development of resistance to vemurafenib and to elucidate the role of circulating HSPA5/GRP78 in drug resistance mechanisms in BRAFV600E-mutated colon cancer." (PMID 37106808, 2023). "Based on this in silico finding, we propose that reduced level of secreted HSPA5/GRP78 should be further investigated as a potential indicator of treatment outcomes in BRAF-mutated colon cancer." (PMID 37106808, 2023). "Although lower mRNA expression levels of several UPR-related proteins identified in this study were found in association with poorer median overall survival of BRAF-mutated colon cancer patients, it was only for HSPA5/GRP78 that this correlation was statistically significant." (PMID 37106808, 2023). "Studies have shown that HSPA5 inhibits the nuclear translocation of ROS and Nrf2 in DLD-1 colon cancer cells, indicating a regulatory role for HSPA5 in cellular responses to oxidative stress." (PMID 39591317, 2024). "GPX4 is a protein associated with poor prognosis, potentially inhibiting ferroptosis in colon cancer cells through specific signaling pathways and interacting synergistically with HSPA5." (PMID 37842645, 2023). "Previously, it was demonstrated that HSPA5/GRP78 inhibition evoked ER stress and apoptosis in a panel of BRAFV600E-mutated colon cancer cell lines." (PMID 37106808, 2023). "Similarly, downregulation of the HSPA5/GRP78 protein expression reduced the viability of BRAF mutant colon cancer cells, which indicates that BRAF-mutated colon cancer cells are dependent on the UPR for survival." (PMID 37106808, 2023). "Increased level of RPA1 and reduced level of HSPA5/GRP78 were the most prominent secretory features of vemurafenib-resistant colon cancer cells, which were also specifically correlated with BRAFV600E genotype and poor survival outcomes in colon cancer patients with BRAFV600E mutation." (PMID 37106808, 2023). "Thus, decreased level of HSPA5/GRP78 may be investigated in future clinical studies as a clinical endpoint to monitor and/or predict treatment efficacy in BRAFV600E-mutated colon cancer patients." (PMID 37106808, 2023). "Further studies are required to investigate the potential of RPA1 and HSPA5/GRP78 in the real-world setting using clinical samples and to examine their roles in determining cancer cell response to BRAFV600E inhibition, not only in colon cancer but also in other BRAFV600E-mutated cancers." (PMID 37106808, 2023). "Moreover, HSPA5 expression on the cell surface of colon cancer is correlated with a poor prognosis." (PMID 27034162, 2016). "Likewise, down-regulation of secretory HSPA5/GRP78 protein emerged in our study as a significant feature associated with chemoresistant phenotype, which was also found in in silico analyses to be correlated with BRAFV600E genotype and poor survival rates in colon cancer patients." (PMID 37106808, 2023). "To determine whether TDA activates endoplasmic reticulum stress in colon cancer cells, we examined the expression of PERK, IRE1α, XBP1 and HSPA5 using Western blot." (PMID 34070303, 2021).
diabetes (74 papers, 2009 to 2025). "Changes in the expression of related HSPs (HSPA8, HSP90AA1, and HSPA5,) have been confirmed in complications of diabetes and are functionally related to hyperglycemia-induced cell damage." (PMID 32851081, 2020). "Through the PPI network screening, it was found that 5 key genes (YWHAZ, HNRNPA1, HSPA8, HSP90AA1, and HSPA5) obtained through protein interactions may provide new ideas for the treatment of diabetes." (PMID 32851081, 2020). "Indeed, HSPA5 inhibitors interfere with SARS-CoV-2 infection, corroborating this hypothesis, while HSPA5 levels might predispose to a severe progression and outcome of COVID-19 in patients with older age, obesity, and diabetes." (PMID 35397534, 2022). "The clinical relevance of heat shock proteins in diabetes is further evidenced by studies showing higher levels of HSP70, HSP27, HSPA5, and HSPA8 in target organs affected by diabetic complications, as identified through this systematic review and meta-analysis." (PMID 39765892, 2024). "We observed that ATF6, CHOP, ERN1, HSPA5, and ATF4 mRNA levels were significantly increased in tissues from subjects with diabetes, and this was supported by an increased expression of ATF6 and CHOP protein expression when compared with tissue from subjects without diabetes." (PMID 33028031, 2020). "Moreover, in insulin resistant subjects with diabetes, despite elevated expression of sXBP1, the SDF2L1/sXBP1 ratio and the HSPA5/sXBP1 ratio were significantly lower." (PMID 30814508, 2019).
pancreatic cancer (70 papers, 2008 to 2025). "SREBF1 (Sterol Regulatory Element Binding Transcription Factor), ASS1 (Argininosuccinate Synthase) and HSPA-5 (Homo Sapiens Heat Shock protein 5) were selected for further validation by RT-qPCR due to their known association with tumor processes and with pancreatic cancer development." (PMID 30913248, 2019). "Exosomal DNAJB11, a co-chaperone to HSPA5, significantly influences pancreatic cancer (PC) progression by enhancing HSPA5’s activity and promoting tumor growth." (PMID 41369326, 2025). "YUM70, another selective HSPA5 inhibitor, attenuated tumor growth in a pancreatic cancer xenograft model." (PMID 37807968, 2023). "Recent reports elucidated that HSPA5 upregulation negatively regulates ferroptosis in pancreatic cancer, while ATF4 activation upregulates HSPA5, thus the HSPA5-GPX4 pathway is one of the causes of gemcitabine resistance." (PMID 36105219, 2022). "HSPA5 (heat shock protein family A member 5) acts on GPX4 to negatively regulate ferroptosis in pancreatic cancer." (PMID 34178977, 2021). "In our study, we found that DNAJB11 reduced the expression of HSPA5 in pancreatic cancer cells." (PMID 36209075, 2022). "A group led by Yuan Wang demonstrated that the acetylation of HSPA5 by EP300 amplified the HSPA5-induced suppression of GPX4, leading to heightened lipid peroxidation and ferroptosis in pancreatic cancer." (PMID 40255561, 2025).
Obesity (68 papers, 2014 to 2026). Accumulation of substantial excess body fat. "Previous studies have reported that HSPA5 abundance was increased in AT of patients with obesity highlighting its direct association between BMI and other metabolic factors including IR or hypertriglyceridemia." (PMID 38703299, 2024). "Dysregulation of HSPA5 is associated with various diseases, such as cancers, cardiovascular diseases, immunological diseases, obesity, neurodegenerative diseases, and stroke." (PMID 37275848, 2023). "Another study on obesity revealed that RTN3 binds to HSPA5 (also called GRP78), which regulates SREBP‐1c activation and promotes lipid synthesis." (PMID 38420163, 2024). "A similar mechanism operates in Hspa5 +/- mice to attenuate diet-induced obesity and insulin resistance." (PMID 37068109, 2023). "The development of high-fat diet-induced obesity and T2D decreases in Hspa5 (heat shock protein family A member 5)-null mice (knockout for BIP)." (PMID 35011666, 2021). "It is conceivable that an altered UPR ‘setpoint’ with reduced expression of Hspa5 and other UPR mRNA targets could render the animals more sensitive to ER stress-induced cell death and exacerbate the hepatic inflammation associated with obesity." (PMID 27938665, 2016). "A literature search with the keywords “GRP78” or “BiP/HSPA5” gave more than 20,000 publications in the Web of Science, PubMed, ACS, Elsevier and Wiley databases, but few using the keywords of “obesity” and “GRP78” or “BiP/HSPA5” (accessed on 15 September 2022)." (PMID 36498048, 2022).
gastric cancer (66 papers, 2007 to 2026). A primary or metastatic malignant neoplasm involving the stomach. "Among these, co-expression patterns involving genes such as CXCR4 and HSPA5 had significant prognostic value in gastric cancer and glioblastoma." (PMID 41948345, 2026). "In gastric cancer, miR-495-3p inhibits cytoprotective autophagy via targeting heat shock protein 70 family protein 5 (HSPA5, also called GRP78)." (PMID 33066509, 2020).
viral infection (66 papers, 2008 to 2025). "Dysregulating the expression of HSPA5 in cancer tissues, particularly in the lungs, could influence the susceptibility to virus infection and its severity." (PMID 37275848, 2023). "Changes in HSPA5 expression levels may affect the susceptibility for virus infection and the severity of COVID-19 disease." (PMID 33767597, 2021). "The expression levels of HSPA5 in different tissues might closely related to the susceptibility and severity of the viral infection." (PMID 33767597, 2021). "Among these, HSPA5 has a plausible functional link to a response to viral infection, as it is involved in the general cellular stress response and plays a role in cellular apoptosis." (PMID 40143353, 2025). "Expression of these proteins was associated with activation of reactive oxygen species synthesis in wild-type cells but inhibition in HSPA5 KD cells during viral infection (Figure 5C1,C2)." (PMID 41303479, 2025). "The antibody against the N-terminus of HSPA5 (N20) can interrupt GP1 binding to HSPA5 and reduce virus infection." (PMID 37275848, 2023). "Viral infection increases HSPA5 translocation to the plasma membrane (PM) and forms a membrane protein complex." (PMID 34122058, 2021). "Post PCV2 infection, we identified 199 differentially expressed lncRNAs, which appear to modify genes associated with viral infection, such as SOD2, TNFAIP3, ARG1, SERPINB2, VLDLR, HSPA5, and LCN2." (PMID 30863688, 2019). "By using a peptide phage display screening, the virus-binding peptide identical to the N-terminal sequence of HSPA5 protein was identified and shown to block the virus infection in both A549 and SW480 cell lines." (PMID 27756316, 2016). "We next focused our attention on GRP78 (Hspa5), also known as BiP, that is a key protein in the UPR, a pathway involved in endoplasmic reticulum (ER) stress, and whose alterations are also linked to viral infection and AD pathogenesis." (PMID 32610629, 2020). "Using a cutoff of greater than 30% increase in viral infection normalized to cell viability in two independent screens, we identified HSPA5, TMED2, SPCS2, and DDIT3 as factors whose overexpression increased DENV infection, indicating rate limitation associated with these important proviral factors." (PMID 29451494, 2018). "To further study the role of HSPA5 in CV-A9 infection, we performed experiments by using immunofluorescence confocal microscopy to localize CV-A9 and HSPA5 during the early stages of the virus infection." (PMID 27756316, 2016). "Therefore, mechanically ventilated COVID-19 patients may be exposed to greater viral infection due to high-stretch-induced increases in HSPA5 and virus proliferation in the lungs." (PMID 36835223, 2023). "During viral infection, the HSPA5 (GRP78) translocated to the cell PM recognizes the SARS-CoV-2 S-protein." (PMID 34122058, 2021). "In the acute phase of viral infection (4 hpi; cluster 2), genes responsive to ER stress, such as HSPA1A, HSPA5, and HERPUD1, were specifically upregulated, suggesting that viral infection affects cellular phenotypes from the early hours after cellular entry." (PMID 33142113, 2020). "PEDF signaling is not well characterized in viral infections but was found to be inhibited in HSPA5 KD cells after IAV infection." (PMID 41303479, 2025).